MIF (macrophage migration inhibitory factor)
Diseases named in the same sentence as MIF in open-access papers (continued):
Sharing a sentence is not in itself a finding about the gene and the disease.
rheumatoid arthritis (continued). "Previous studies reported MIF’s role in inflammatory and immune mediated diseases such as rheumatoid arthritis, cancer, multiple sclerosis, systemic lupus erythematosus (SLE), and psoriasis." (PMID 41159021, 2025). "This role of MIF has been previously demonstrated in other autoimmune and inflammatory conditions, such as multiple sclerosis, rheumatoid arthritis and systemic sclerosis." (PMID 40421032, 2025). "In autoimmune inflammatory diseases, such as multiple sclerosis, rheumatoid arthritis, systemic lupus, and asthma, MIF has also been reported as a modifier of interest, particularly in males." (PMID 40225935, 2024). "Both CD74 and MIF have been extensively studied in the context of rheumatoid arthritis, and MIF is now recognized as a crucial player in the development of this disease." (PMID 38730725, 2024). "Experimental and clinical studies on treatments targeting MIF and its receptors demonstrate efficacy in the therapy of rheumatoid arthritis (RA) and systemic lupus erythematosus (SLE)." (PMID 37946732, 2023). "One study performed by Onodera and colleagues previously reported that MIF can influence the mRNA levels of TIMP-1 in a dose-dependent manner in rheumatoid arthritis synovial fibroblasts." (PMID 37508563, 2023). "Two studies reported higher MIF serum levels in sex-balanced groups of patients with rheumatoid arthritis or juvenile idiopathic arthritis who are carriers of the rs755622 minor allele, but sex-separated analyses were not performed." (PMID 36555097, 2022). "Today, it is proven that MIF has a key role in both immune and inflammatory responses and it is involved in numerous conditions, such as asthma, rheumatoid arthritis, sepsis, atopic dermatitis, atherosclerosis and breast cancer." (PMID 35465102, 2022). "Because of this, numerous studies have been conducted to investigate the role of MIF in diseases, particularly autoimmune disorders such as rheumatoid arthritis (RA) and systemic lupus erythematosus (SLE) where GC therapy is required." (PMID 33610191, 2021). "Macrophage migration inhibitory factor (MIF) significantly contributes to rheumatoid arthritis (RA) pathogenesis." (PMID 35011861, 2021). "Previous studies demonstrated that the concentrations of MIF in serum and local tissue were significantly elevated in asthma, atopic dermatitis, rheumatoid arthritis, and systemic lupus erythematosus." (PMID 34305594, 2021). "As revealed by another GWAS, the involvement of ITPR3 in the release of the macrophage migration inhibitory factor (MIF) confirmed the role of this receptor in rheumatoid arthritis." (PMID 32290556, 2020). "Several studies have focused on MIF as a key molecule promoting pathogenesis of a diverse array of diseases, including rheumatoid arthritis and septic shock." (PMID 33046033, 2020). "Macrophage migration inhibitory factor (MIF) is known to participate in immune‐mediated diseases, including rheumatoid arthritis, systemic lupus erythematosus, and some autoimmune skin diseases." (PMID 32705792, 2020). "Studies have shown that MIF is an enhancer of osteoclastogenesis by upregulating the signaling pathway of NF-kB in a periodontitis model and a rheumatoid arthritis model in mice." (PMID 30868074, 2019). "MIF modulates various inflammatory and immune responses, which has prompted the characterization of MIF as a biomarker in several chronic inflammatory diseases, such as rheumatoid arthritis, systemic sclerosis, and inflammatory bowel disease." (PMID 31370326, 2019). "Several studies have shown that MIF is a key modulator in many acute and chronic inflammatory diseases including septic shock, rheumatoid arthritis, systemic lupus erythematosus and atopy." (PMID 30483634, 2017). "The MIF C/7-CATT haplotype is also associated with asthma, juvenile idiopathic arthritis, rheumatoid arthritis, systemic lupus erythematosus, and skin diseases, such as psoriasis and extensive alopecia areata." (PMID 27598332, 2016).
rheumatoid arthritis (continued). "MIF is abundantly expressed in the plasma and synovial tissue of rheumatoid arthritis patients where it correlates with disease activity." (PMID 25821795, 2015). "Although MIF has been shown to have a critical role in recruiting inflammatory immune cells in diseases such as rheumatoid arthritis, the biological role of IL-16 in autoimmune diseases still needs to be unraveled." (PMID 27551482, 2015). "Serum levels of MIF have been shown to be elevated in several autoimmune disorders including rheumatoid arthritis, Wegener’s granulomatosis and systemic lupus erythematosus." (PMID 25506398, 2014). "MIF plays a significant role in immune and inflammatory-based diseases such as asthma, rheumatoid arthritis, acute respiratory distress syndrome and septic shock." (PMID 25503271, 2014). "One of the first clinical studies regarding MIF expression in autoimmunity was in patients with rheumatoid arthritis." (PMID 25506398, 2014). "MIF is an important multifunctional cytokine involved in many physiopathologic processes, such as rheumatoid arthritis, inflammatory bowel disease and septic shock." (PMID 22952837, 2012). "Macrophage migration inhibitory factor (MIF) plays a crucial role in rheumatoid arthritis (RA) pathogenesis, linking the innate and adaptive immune responses." (PMID 21401926, 2011). "Recently, anti-TNF therapy resulted in reduced serum MIF levels in patients with rheumatoid arthritis." (PMID 21152395, 2010). "Two polymorphisms in the promoter region of MIF gene have shown correlation with the worsening of autoimmune and inflammatory diseases such as systemic lupus erythematosus (SLE), rheumatoid arthritis (RA) and psoriatic arthritis (PsA) in Mexican-Mestizo population." (PMID 38178143, 2024). "Altered MIF expression has been implicated in numerous diseases, ranging from inflammatory disorders such as JIA, lupus, and rheumatoid arthritis to organ pathologies such as heart failure, myocardial infarction, acute kidney injury, organ fibrosis, and various malignancies." (PMID 38751447, 2024). "In the treatment of rheumatoid arthritis, isopsoralen (in vitro: 10, 20 μM; in vivo: 5, 20 mg/kg) could improve inflammatory response by targeting macrophage migration inhibitory factor (MIF) and reducing the release of inflammatory factors." (PMID 36627680, 2023). "Whether the MIF-mediated peripheral inflammation, including rheumatoid arthritis and systemic lupus erythematosus, correlates with the aberrant activation of thrombin deserves further study." (PMID 35624475, 2022). "Prior studies showed that immunotherapy and corticosteroid treatments could reduce the circulating MIF levels and attenuate inflammatory responses via regulating the Th1/Th2 inflammation balance in nasal polyps and rheumatoid arthritis." (PMID 34305594, 2021). "For example, MIF is reported to induce rheumatoid arthritis synovial fibroblast MMPs production." (PMID 33601337, 2021). "MIF has also been implicated in non-tumor associated IL-17 expression in a variety of autoimmune disorders including Hashimoto’s thyroiditis and rheumatoid arthritis (RA) where Th17 responses are well-characterized to drive pro-inflammation." (PMID 33324425, 2020). "Previous research has shown that MIF can participate in the pathophysiology of chronic degenerative and autoimmune diseases by significantly increasing body fluids, as in rheumatoid arthritis, diabetes type 1 and 2, metabolic syndrome and oral squamous cell carcinoma, among others." (PMID 30868074, 2019). "Apart from its physiological role as a counter-regulator of GC effects, elevated MIF expression seems to play a major role in several autoimmune disorders, including rheumatoid arthritis and autoimmune hepatitis, and renders anti-MIF treatment a promising therapeutic strategy." (PMID 30475854, 2018). "Rheumatoid arthritis is also characterized by an increased activity of MIF." (PMID 25821795, 2015).
rheumatoid arthritis (continued). "Moreover, impaired efferocytosis, as well as elevated expression levels of IL-1650,51 and MIF,52,53 have been observed to be connected with increased disease severity in autoimmune diseases such as rheumatoid arthritis and systemic lupus erythematosus." (PMID 27551482, 2015). "MIF also induces the rheumatoid arthritis synovial fibroblast MMP-2 expression." (PMID 24586879, 2014). "Also, high levels of MIF showed good correlation with CRP in the sera from patients with rheumatoid arthritis." (PMID 23451183, 2013). "This partly differs from the previous finding that the MIF alleles, -173*C or -794 CATT7, are associated with the incidence or severity of a number of inflammatory conditions, including rheumatoid arthritis, juvenile inflammatory arthritis, inflammatory bowel disease, celiac disease and asthma." (PMID 23721694, 2013). "Indeed, increased MIF plasma or serum levels were identified in patients with severe sepsis, Crohn's disease and ulcerative colitis, acute pancreatitis,rheumatoid arthritis (RA), type 2 diabetes (T2D), Guillain-Barresyndrome, or multiple sclerosis." (PMID 18317509, 2007). "Other genes (HAVCRI, CTLA4, SUMO4, MAP3K7IP2, PAID4, chromosome 5 locus, MIF) may also contribute to the development of rheumatoid arthritis directly or within the context of smoking." (PMID 18466513, 2007). "Indeed, it has been reported that MIF expression increase, which is positively correlated to the number of CATT repeats and the activity of the MIF promoter, is associated with an enhanced severity and risk for rheumatoid arthritis." (PMID 39132307, 2024). "Macrophage migration inhibitory factor (MIF) is a procytokine that mediates pleiotropic inflammatory effects in inflammatory diseases such as rheumatoid arthritis (RA) and ankylosing spondylitis (AS)." (PMID 33610191, 2021). "Furthermore, macrophage migration inhibitory factor (MIF), which has primarily been known for its proinflammatory effects in autoimmune diseases such as multiple sclerosis and rheumatoid arthritis, has been shown to play important roles in regulating tumor microenvironment 41-44." (PMID 32550907, 2020). "Of note, MIF could also be a therapeutic target in a number of immune-related pathologies such as asthma, rheumatoid arthritis, chronic colitis, ulcerative colitis, glomerulonephritis, and lupus erythematosus, highlighting the possible clinical significance of the present study." (PMID 31248381, 2019). "Hence, it was hypothesized that MIF plays important roles in a number of diseases, including chronic renal disease, asthma, rheumatoid arthritis, inflammatory bowel diseases, systemic lupus erythematosus and crescentic glomerulonephritis." (PMID 31248381, 2019). "Previous studies have reported that circulating MIF levels are elevated in rheumatoid arthritis (RA), systemic lupus erythematous (SLE), insulin resistance (IR), and type 2 diabetes mellitus (T2DM)." (PMID 25972622, 2015). "Of note, both IL-8 and MIF have consistently been implicated in propagating inflammatory cascades in Inflammatory Bowel Disease (IBD), Rheumatoid Arthritis (RA), Systemic Lupus Erythematosus (SLE)." (PMID 35052454, 2022). "Therefore, MIF is involved in the pathogenesis of many autoimmune and inflammatory diseases, including rheumatoid arthritis (RA), liver injury, and pancreatitis." (PMID 36160453, 2022). "Similar studies have been conducted in other immunological diseases; in rheumatoid arthritis, ADA treatment resulted in reductions in plasma levels of chemerin, correlated with decreases in IL-6 and macrophage migration inhibitory factor concentrations." (PMID 34640632, 2021). "MIF is a key mediator of various inflammatory diseases that varies form autoimmune diseases such as Rheumatoid Arthritis (RA), Systemic Sclerosis (SS), Systemic Lupus Erythematosus (SLE) and Multiple Sclerosis (MS), to infectious diseases such as Malaria, Tuberculosis, Leishmania and others." (PMID 34662363, 2021).
rheumatoid arthritis (continued). "Moreover, patients with rheumatoid arthritis (RA) also exhibit increased MIF, and this increase is correlated with TM and MIF production." (PMID 23383040, 2013). "Animal studies using collagen-induced arthritis as a rheumatoid arthritis model found that the severity of rheumatoid arthritis was reduced in the absence of MIF." (PMID 40605976, 2025). "Similarly, the macrophage migration inhibitory factor (MIF) has recently been shown to be associated with protection against O/A and may also be important in modulating autoimmune reactions such as those associated with rheumatoid arthritis, lupus or giant cell arthritis." (PMID 33806897, 2021). "Before lumbar puncture, two out of 171 patients – one with pneumococcal meningitis (CSF MIF level 51,539 ng/l) and one with VZV encephalitis (CSF MIF level 5,042 ng/l) received therapy with prednisolone 5 mg/day for treatment of rheumatoid arthritis and chronic myeloid leukaemia, respectively." (PMID 19558639, 2009). "In rheumatoid arthritis (RA) fibroblastic-like synoviocytes (FLS), MIF upregulates PLA2G4A activity and PLA2G4A mRNA expression." (PMID 40417665, 2025). "In addition, baicalein inhibits human rheumatoid arthritis fibroblast-like synoviocytes (RAFLS) proliferation involving suppression of nuclear factor kappa B (NF-κB) transcriptional activity and recombinant macrophage migration inhibitory factor- (MIF-) mediated signaling." (PMID 33204288, 2020). "MIF is also an immunoregulatory cytokine, playing an important role in autoimmune and inflammation-related diseases, including inflammatory bowel diseases (IBD), systemic lupus erythematosus (SLE), rheumatoid arthritis (RA), type 1 diabetes mellitus, and multiple sclerosis (MS)." (PMID 30983881, 2019). "Macrophage migration inhibitory factor (MIF) is one of key regulators in acute and chronic immune-inflammatory conditions including rheumatoid arthritis (RA)." (PMID 21401926, 2011). "Interestingly, while the inflammatory state may affect preheparin LPL mass in rheumatoid arthritis, MIF-regulated LPL transcription is independent of inflammation." (PMID 38973609, 2024).
breast cancer (109 papers, 2007 to 2026). A primary or metastatic malignant neoplasm involving the breast. "In breast cancer, high expression of MIF is associated with the invasiveness of tumor cells and poor prognosis." (PMID 40110199, 2025). "Elevated MIF expression supported tumor growth while a loss of MIF promoted the anti-tumor immune infiltration of CD4 + /CD8 + T cells producing IFN in breast cancer." (PMID 38685050, 2024). "We found an inverse association between genetically proxied MIF concentrations and breast cancer risk." (PMID 35012533, 2022). "This anti-tumor phenotype associated with MIF-deficient 4T1 breast cancer tumors was attributed to the elicitation of significantly fewer intratumoral M-MDSCs in both the in vivo breast cancer models and in an in vitro model of M-MDSC differentiation." (PMID 33324425, 2020). "To clarify the causal involvement of MIF in breast cancer, we investigated the role of MIF and its receptor CD74 in cytokine production, proliferation, and invasion of invasive versus non-invasive breast cancer cells." (PMID 19602265, 2009). "MIF overexpression is observed in breast cancer but its causal role in the development of this tumour entity is unclear." (PMID 19602265, 2009). "MIF has been implicated in prostate, lung and breast cancer with overexpression shown to correlate with tumor grade/stage and prognosis." (PMID 17650334, 2007). "Despite findings from several experimental studies suggesting a positive association, our study showed an inverse association for genetically proxied circulating MIF concentrations in relation to breast cancer and a similar observation was made in another study using the MR approach." (PMID 35012533, 2022). "However, in previous studies contradictory and uncertain results have been presented on the implication of MIF polymorphisms with the association in cancer, specifically in breast cancer (BC)." (PMID 31978276, 2020). "MIF levels are associated with an increased incidence of prostate cancer, non small cell lung cancer, squamous cell carcinomas of the nasopharynx and esophagus, breast cancer, colorectal cancer, hepatocellular carcinoma and several other cancers." (PMID 26267609, 2015). "Moreover, systemic injection of the nanoparticles into the Balb/c mice bearing 4T1 mammary tumors resulted in the MIF reduction in tumor-associated macrophages." (PMID 25799489, 2015). "A recent study suggested that intracellular MIF levels are low in aggressive breast cancer cell lines and that cytosolic MIF expression associates with an increase of recurrence-free survival patients, whereas extracellular MIF promotes migration and invasion of breast cancer cells." (PMID 23174366, 2012). "However, the association between MIF serum levels or MIF expression within breast cancer tissue and breast cancer progression in humans has been controversial." (PMID 19602265, 2009). "Elevated MIF expression in breast cancer tissues and cells is correlated with poorer patient outcomes, especially in cases of triple-negative breast cancer." (PMID 41597203, 2026). "While invasive breast cancers typically rely on high CD74 to maximize MIF-driven EMT, our results raise the possibility that ERα+ tumors such as MCF7 cells achieve similar outcomes through WISP1-mediated MIF amplification." (PMID 41597235, 2026). "MIF primarily exerts its effects through interaction with the CD74 receptor, which is frequently upregulated in breast cancer and has been particularly associated with aggressive tumor features, including increased lymph-node invasion." (PMID 41597235, 2026). "Elevated levels of MIF are found in several cancers, including breast cancer, where increased MIF concentrations in both tumor tissues and the bloodstream are associated with poor prognosis." (PMID 41597235, 2026). "MIF contributes to breast cancer development by enhancing tumor cell proliferation, metastasis, and blood vessel formation, while also shaping the TME." (PMID 41597203, 2026).